NTN1 (netrin 1)
Diseases named in the same sentence as NTN1 in open-access papers (continued):
Sharing a sentence is not in itself a finding about the gene and the disease.
diabetes (continued). "In diabetic mice, expression of netrin-1 was decreased in the aorta but, overexpression of netrin-1 prevented from diabetes-induced vascular damage and attenuated high glucose-induced oxidative stress." (PMID 30532735, 2018). "Our findings clearly indicate that netrin-1 enhances eNOS activity by a posttranslational mechanism and reduces vascular ROS in diabetes/hyperglycemia." (PMID 29059224, 2017). "We observed that netrin-1 is expressed in the vascular aorta and BAECs, and that its expression is markedly decreased by diabetes/hyperglycemia." (PMID 29059224, 2017). "In summary, our study clearly shows that diabetes decreases vascular netrin-1 levels and that overexpression of netrin-1 attenuates diabetes-induced VED." (PMID 29059224, 2017). "Our data suggest that netrin-1 decreases inflammation through inhibition of NFκB activation, attenuates diabetes-induced COX-2 expression and suppresses apoptotic processes by reducing p16INK4A and caspase-3 activity and expression." (PMID 29059224, 2017). "In contrast, long term netrin-1 treatment in mice showed a preventive role against high-fat diet/STZ-induced diabetes through maintained islet insulin secretion and reduction of vascular inflammation." (PMID 29059224, 2017). "Reduction of vascular netrin-1 levels in diabetic WT mice appears to be involved in impaired endothelial function because overexpression of netrin-1 in mice largely prevents diabetes-induced endothelial impairment." (PMID 29059224, 2017). "In previous studies, it was shown that netrin-1 protein is induced in proximal tubular epithelial cells and excreted in urine during diabetes before microalbuminuria onset both in animal models and in humans." (PMID 27087488, 2016). "Previous studies from our lab determined that netrin-1 protein is induced in epithelial cells and excreted in urine during diabetes both in animal model and in humans." (PMID 24991088, 2014). "Netrin- 1, a laminin-like protein, is a potent anti-inflammatory protein that plays an important protective role against metabolic dysfunction, insulin resistance, diabetes, and cardiovascular diseases." (PMID 40332546, 2025). "In addition, netrin-1-treated diabetic mice presented a substantial reduction in macrophage infiltration in pancreatic islets and a decrease in circulating TNF-α levels, showing the anti-inflammatory action of netrin-1 in diabetes." (PMID 30532735, 2018). "Overexpression of netrin-1 in kidney proximal tubule suppressed inflammation and albuminuria through suppression of diabetes-induced cyclooxygenase-2 (COX-2) expression and prostaglandin E2 (PGE2) production by inhibiting nuclear factor kappa B (NF-kB) activation." (PMID 30532735, 2018). "We assessed whether the protective effect of netrin-1 in diabetes-induced VED involves down-regulation of expression and activity of arginase." (PMID 29059224, 2017). "Enhancement of netrin-1 function may be a useful therapeutic means for preventing vascular dysfunction in diabetes." (PMID 29059224, 2017). "This study provides strong evidence of a vaso-protective action of netrin-1 in diabetes." (PMID 29059224, 2017). "We conclude that enhancement of netrin-1 may represent a useful therapeutic means for restoring vascular function in diabetes and potentially other diabetic complications." (PMID 29059224, 2017). "However, overexpression of netrin-1 attenuates diabetes-induced VED and limits the reduction of NO levels, while increasing expression of p-ERK1/2, and suppressing oxidative stress and inflammatory and apoptotic processes." (PMID 29059224, 2017). "In addition, urinary netrin-1 was elevated early in the time course of rat and human diabetes." (PMID 30532735, 2018). "Thus, our results indicate that enhancement of netrin-1 effects in hyperglycemia/diabetes may represent a therapeutic means for amelioration of endothelial cell dysfunction." (PMID 29059224, 2017).
diabetes (continued). "In addition, diabetes downregulated circulating levels of netrin-1 in two different genetic models." (PMID 24991088, 2014). "Moreover, overexpression of netrin-1 in tubular epithelial cells before the start of the disease process suppressed diabetes induced increase in infiltration of neutrophils and macrophages, chemokine expression, albuminuria, and tubular epithelial cell apoptosis in kidneys." (PMID 24991088, 2014). "Suppression of netrin-1 and elevation of DCC levels during diabetes allows DCC to promote apoptosis." (PMID 29059224, 2017). "We observed that diabetes markedly increased NFκB and COX-2 expression in WT mice, but expression levels were significantly lower in mice overexpressing netrin-1." (PMID 29059224, 2017). "Overexpression of netrin-1 prevented diabetes-induced VED in aorta from diabetic mice and netrin-1 treatment attenuated HG-induced impairment of nitric oxide synthase (NOS) function in BAECs." (PMID 29059224, 2017). "Moreover, recent studies suggest that Netrin-1 may become a therapeutic target in the treatment of various pathologies, either as a stimulant or inhibitor of angiogenesis such as in diabetes or cancer, respectively, even protecting the heart against ischemia-reperfusion injury." (PMID 28241866, 2017). "This review will focus on one such counteractive anti-inflammatory pathway netrin-1 and its receptor UNC5B in the regulation of inflammation during acute (ischemic, drug induced) and chronic (diabetes) kidney injury." (PMID 24991088, 2014). "Consistent with downregulation of plasma netrin-1, both netrin-1 and UNC5B mRNA were found to be significantly downregulated in diabetic kidney as compared to control." (PMID 24991088, 2014). "Previously, Ay and colleagues reported that serum netrin-1 levels were raised in patients with diabetes whose mean HbA1c level was 8.1% compared to non-diabetic patients." (PMID 30532735, 2018). "In addition, diabetes induced a large increase in the excretion of prostaglandin E2 (PGE2) in urine, which was suppressed in netrin-1 transgenic mice." (PMID 24991088, 2014). "However, there is no longitudinal study of changes in netrin-1 levels during the development of diabetes and insulin resistance, and the role of netrin-1 in the pathophysiology of type 2 diabetes is unclear." (PMID 30532735, 2018). "Also, there was a strong positive correlation between plasma netrin-1 level and HbA1c, and a significant negative correlation between eGFR, but the study sample was relatively small and a comparative group (such as pre-diabetes) was not included." (PMID 30532735, 2018). "In the event of this regard, netrin-1 may be useful in treating patients with T2DM or without diabetes but with insulin resistance." (PMID 27255377, 2016). "The regulation of netrin-1 and its receptor in the kidney during diabetes is not clearly defined." (PMID 24991088, 2014). "However, since the role of netrin-1 in diabetes-induced BBB dysfunction has not been well documented, future studies are necessary to determine if increased netrin-1 levels represent a therapeutic strategy to prevent BBB disruption and CNS inflammation." (PMID 29059224, 2017).
ischemic stroke (20 papers, 2017 to 2025). A stroke disorder caused by obstruction of blood flow to the brain, due to thrombotic (local blood clot formation) or embolic (due to a blood clot or other material traveling from another site) event. "A high serum netrin-1 concentration lowers the risk of ischaemic stroke and is negatively associated with outcomes after ischaemic stroke." (PMID 38534778, 2024). "Lower serum Netrin-1 concentrations have been independently associated with worse functional outcomes and increased mortality in various neurological disorders, including ischemic stroke, intracerebral hemorrhage, and subarachnoid hemorrhage." (PMID 40714984, 2025). "Recent evidence shows that serum NTN‐1 was associated with recovery after ischemic stroke." (PMID 36852451, 2023). "Afterwards, we investigated whether administering AAVPHP.B-pTMEM119-Netrin-1 to mice could improve their survival and protect against neuron loss following ischemic stroke." (PMID 37388740, 2023). "Additionally, some research output suggested that Netrin-1 is implicated in immune response, which is supposed to be an important element of ischemic stroke progression." (PMID 30320139, 2018). "In addition to netrin-1 causing activation of eNOS, prior studies have shown that it is a key regulator of inflammation and apoptosis in ischemic stroke, hypoxic mesenchymal stem cells and diabetic nephropathy." (PMID 29059224, 2017). "Previous studies have shown microglial expression of netrin-1 and UNC5a in clinical patients during an ischemic stroke and in rodent models of experimental ischemic stroke." (PMID 40723793, 2025). "Keywords such as ischemic stroke, biomarkers, neurofilament light chain (NfL), bilirubin, thioredoxin, netrin-1, omentin-1, circular RNA, diffusion tensor imaging, EEG, TMS, motor recovery, and machine learning." (PMID 41303115, 2025). "Netrin-1 exerts its neuroprotective effects by activating various anti-apoptotic pathways in response to ischemic stroke." (PMID 38672167, 2024). "Collectively, Netrin-1 appears to mitigate neurological decline post ischemic stroke by influencing blood–brain barrier permeability, endothelial function, inflammation, and angiogenesis." (PMID 38672167, 2024). "Netrin-1-induced phenotypic change in microglia exerted protective effects on neuronal cells in vivo during ischemic stroke." (PMID 37388740, 2023). "Further research is needed to elucidate the specific signaling mechanisms of Netrin-1 through its receptors and to explore the potential of targeting Netrin-1 in the treatment of ischemic stroke." (PMID 37388740, 2023). "Mice were given AAVPHP.B-pTMEM119-Netrin-1 or AAVPHP.B-pTMEM119-Scr three days before inducing ischemic stroke by MCAO, and after reperfusion for 72 hours, the mice were analyzed." (PMID 37388740, 2023). "Taken together, these data suggest that AAVPHP.B-pTMEM119-Netrin-1 can alleviate experimental ischemic stroke in mice, likely by modulating microglial phenotype." (PMID 37388740, 2023). "A microglia-specific gene targeting approach and a delivery system allowing for crossing the blood-brain barrier were applied in a mouse model for ischemic stroke to investigate the role of microglial Netrin-1." (PMID 37388740, 2023). "In conclusion, our studies suggested that engrafted OPCs promoted the recovery after ischemic stroke by enhancing endogenous oligodendrogenesis, neurite growth, and synaptogenesis; the last two being mediated by the Netrin-1/DCC axis." (PMID 34881088, 2021). "In a model of ischemic stroke, overexpression of netrin-1 promoted long-time recovery by improving oligodendrogenesis and repair of white matter damage." (PMID 33183353, 2020). "Our results indicate that netrin-1 is an important molecule in regulating astrocyte activation and neuroinflammation in cerebral ischemia and provides a potential target for ischemic stroke therapy." (PMID 30227858, 2018).
ischemic stroke (continued). "In summary, the present study favors the results that netrin-1 ameliorated the impairment of BBB secondary to ischemic stroke by promoting tight junction function and endothelial survival." (PMID 29311781, 2017). "Our results showed that netrin-1 ameliorated BBB impairment secondary to ischemic stroke by promoting tight junction function and endothelial survival." (PMID 29311781, 2017). "Therefore, our results suggest that cerebral microglia from experimental rodents with ischemic stroke exhibit an increased expression of Netrin-1 and its receptor UNC5a." (PMID 37388740, 2023). "Notably, in both ischemic stroke and subarachnoid hemorrhage models, up-regulation of Netrin-1 and its receptors was observed around the injury site, which was opposite to the changes in peripheral blood." (PMID 35806983, 2022). "In recent years, findings have shown that Netrin-1 plays a neuroprotective role following middle cerebral artery occlusion in mice either by decreasing the size of the infarct to enhance recovery, or attenuating ischemic stroke-induced apoptosis." (PMID 29209172, 2017). "The present study was taken to observe the temporal process of BBB impairment secondary to ischemic stroke, and to investigate whether netrin-1 could protect BBB against secondary injury in vivo and in vitro." (PMID 29311781, 2017). "With increasing developments in research, the neuroprotective effect of Netrin-1 was discovered, evidenced by the reduction in infarct size or attenuation of ischemic stroke-induced neuronal apoptosis to promote angiogenesis in mice after middle cerebral artery occlusion." (PMID 29209172, 2017). "While the role of neuronal Netrin-1 in brain development and post-ischemic survival is well-established, the specific function of microglial Netrin-1 in ischemic stroke is not yet clear and thus addressed in the current study." (PMID 37388740, 2023). "This study aimed to investigate the role of microglial Netrin-1 in ischemic stroke, a topic that has not been fully understood." (PMID 37388740, 2023). "While the role of neuronal Netrin-1 in brain development and post-ischemic survival is well-established, the specific function of microglial Netrin-1 in ischemic stroke is not yet clear." (PMID 37388740, 2023). "Taken together, we hypothesize that netrin-1 and its receptor DCC may also be involved in the beneficial effects of ADSC transplantation on the neurological recovery after ischemic stroke in rats." (PMID 29017609, 2017). "To determine whether netrin-1 and DCC are involved in the neural protection induced by ADSC transplantation after ischemic stroke, we measured their temporal and spatial expression patterns in the brains of MCAO rats." (PMID 29017609, 2017).
breast carcinoma (19 papers, 2011 to 2025). "Netrin-1 is a 60–80 kD laminin-like protein implicated in promoting cell invasion and angiogenesis and inhibiting apoptosis in glioblastoma, lung cancer and breast cancer." (PMID 27846823, 2016). "Interestingly, in the panel of breast cancers analyzed in the current study, low levels of NTN1 expression are associated with the hypermethylation of the CpG island located in the 5′‐end of this gene." (PMID 27378792, 2016). "There is evidence that NTN1 may serve as a diagnostic marker for breast cancer." (PMID 38546656, 2024). "It was also reported that netrin-1 was upregulated in multiple malignancies including glioma, breast cancer, ovarian malignancies, non-small cell lung cancer, hepatocellular carcinoma, melanoma and medulloblastoma which was consistent with our results." (PMID 35974411, 2022). "In contrast, NTN1 expression was higher in TNBCs compared with normal breast or luminal breast cancers." (PMID 29720215, 2018). "Altogether, these data strongly suggest that DNA hypermethylation is involved in the transcriptional silencing of DAPK1 and NTN1 in human breast cancer cells." (PMID 27378792, 2016). "The relationship between DAPK1/NTN1 downregulation and DNA hypermethylation was also observed in a larger number of breast cancer samples (n = 807) available on TCGA data portal." (PMID 27378792, 2016). "Breast cancer cells that over-express the signaling-defective integrin β4-1355T mutant mimic the netrin-1-over-expressing cells used here in the arrested tumor growth in vivo and the unaffected cell proliferation in normal cultures in vitro." (PMID 27034160, 2016). "Although the combination of netrin-1 and neogenin plays a significant role during this process, the role of neogenin in breast cancer remains to be determined." (PMID 25416629, 2014). "In recent years, netrin-1 has been found effective in inhibiting apoptosis in lung cancer, advanced neuroblastoma, breast cancer and prostate cancer." (PMID 24528886, 2014). "Moreover, blocking immune-suppressor-inducing molecules, such as netrin-1, suppressed resistance to chemotherapy and immune checkpoint inhibitors in a breast cancer model." (PMID 39598436, 2024). "Along this line, UNC5B overexpression in breast cancer as observed in our study could be a selective advantage for tumorigenesis, as increased expression of netrin-1 was seen in the majority of breast tumors with metastatic tendency." (PMID 32902412, 2020). "Furthermore, higher Netrin-1 expression has been correlated with invasion and metastasis in distant sites in colon carcinoma, adenoma, pancreatic ductal adenocarcinoma and breast cancer." (PMID 32545553, 2020). "Analyses of TCGA dataset showed elevated expression of UNC5A in luminal breast cancers, and NTN1 overexpression in TNBCs and E2 could further enhance luminal expression of UNC5A." (PMID 29720215, 2018). "Thus, the UNC5A–NTN1 signaling axis is likely tilted more towards UNC5A-activated signals in ERα+/PR+ breast cancers and NTN1-generated signals in TNBC/ER− tumors." (PMID 29720215, 2018). "UNC5A and NTN1 are described as tumor suppressor and oncogene, respectively, in breast cancer." (PMID 29720215, 2018). "Interestingly, few recent studies showed that NTN1 may also promote cancer by increasing survival and resistance of lung and breast cancer cells to apoptosis." (PMID 21789787, 2011). "To date, roles for only NTN1 and NTN4 have been described in breast cancer, ovarian cancer, prostate cancer, and pancreatic cancer among endocrine system-related tumors and sex hormone-targeting tumors." (PMID 32251318, 2020). "Up-regulated expression of netrin-1 and UNC5B has been observed in breast cancer patients with distant metastasis." (PMID 27846823, 2016). "Altogether, these data suggested that DNA methylation is involved in the downregulation of NTN1 and DAPK1 in human breast cancers." (PMID 27378792, 2016).
breast carcinoma (continued). "However, we found that netrin-1 induced the anti-apoptotic effect of B-ALL cells, and this effect of netrin-1 was also discovered in lung cancer, advanced neuroblastoma and breast cancer, in which the expression of netrin-1 was also upregulated." (PMID 35974411, 2022). "Comparing different subtypes of brain metastases, highest netrin-1 levels were detected in secondary brain tumors deriving from the lung followed by breast carcinomas and carcinomas which were not otherwise specified (NOS)." (PMID 24647424, 2014). "The involvement of netrin-1 in the spread of cancer cells was corroborated by the finding that especially metastatic breast carcinomas show netrin-1 overexpression compared to their non-metastatic counterparts." (PMID 24647424, 2014).